PAFAH1B3 (platelet activating factor acetylhydrolase 1b catalytic subunit 3)
Diseases named in the same sentence as PAFAH1B3 in open-access papers (continued):
Sharing a sentence is not in itself a finding about the gene and the disease.
tumor (continued). "Drawing from our proteomic analysis, we discerned a pronounced overexpression of PAFAH1B3 within LUAD tumors (90 %, 18/20) and detected a substantial presence of this protein in exosomes emanating from the tumor tissues (85 %, 17/20)." (PMID 39553628, 2024). "As previously noted, PAFAH1B3 was markedly upregulated in LUAD tissues and predominated within exosomes, hinting at its pivotal role within the tumor microenvironment mediated by exosomal dissemination." (PMID 39553628, 2024). "In conclusion, our data highlighted PAFAH1B3 as a potential prognostic biomarker in LUAD, pointing to its dual signature of high expression in tumor tissues and pronounced exosomal release as a harbinger of poor patient prognosis." (PMID 39553628, 2024). "The expression of the PAFAH1B3 protein in HCC was variable, and the positive rate was greater in tumor tissues than in normal tissues." (PMID 38063949, 2023). "Based on the results of the CellMiner analysis, which allowed us to identify nine tumor-sensitive drugs, Milciclib had lower IC50 values in patients with high PAFAH1B3 expression." (PMID 38063949, 2023). "We discovered that PAFAH1B3, ZIC2, and ESR1 were significantly different in tumor and normal tissues, which is consistent with the findings of the bioinformatic analysis." (PMID 37957420, 2023). "The effectiveness of treatment is enhanced by PAFAH1B3 blockade, which reduces the proliferation of HCC tumor cells." (PMID 37957420, 2023). "High expression of PAFAH1B3 had a worse OS for most clinical and demographic NSCLC subgroups including pathologic stage, TN stage, residual tumor, gender, age, smoking status, and race." (PMID 35187070, 2021). "A nomogram was created to integrate PAFAH1B3 as a LIHC biomarker, including the TNM stages, tumor status, histologic stage to predict OS, DSS, and PFI." (PMID 35187070, 2021). "Higher expression of PAFAH1B3 had a worse OS in most clinical and demographic subgroups of NSCLC, including pathologic stage, TN stage, residual tumor, gender, age, smoking status, and race." (PMID 35187070, 2021). "Besides, high expression of PAFAH1B3 predicted the poor prognosis of patients with HCC and showed that it was related to tumor stage and survival rate." (PMID 34490100, 2021). "In addition, overexpression of PAFAH1B3 had a worse OS in most clinical and demographic subgroups of LIHC, including pathologic stage, histologic stage, TNM stage, residual tumor, gender, age, adjacent hepatic tissue inflammation, height, and weight." (PMID 35187070, 2021). "Moreover, PAFAH1B3 was significantly overrepresented not just in tumor tissues and their released exosomes but also displayed abnormally elevated mRNA levels in the TCGA LUAD database and two GEO cohorts, positioning it as a strong indicator of dismal patient prognosis." (PMID 39553628, 2024). "The results of qRT-PCR and IHC analysis showed that PAFAH1B3, ZIC2, and ESR1 were differentially expressed in HCC and normal tissues and that patients with high TEXSRGs-scores had higher TEX infiltration abundance and tumor stemness gene expression." (PMID 37957420, 2023).
PAFAH1B3 also shares sentences with these, for which no sentence is quoted: colon cancer (2 papers); sarcoma (2); skin cutaneous Melanoma (2); acute myeloid leukemia (1); adrenocortical carcinoma (1); Atrophy (1); Brain atrophy (1); breast tumors (1); cervical squamous cell carcinoma (1); clear cell renal cell carcinoma (1); cognitive deficits (1); cryoglobulinemia (1); Diamond-Blackfan anemia (1); diffuse large B-cell lymphoma (1); glioblastoma (1); head and neck squamous cell carcinoma (1); infection (1); low grade glioma (1); lymph node metastasis (1); non-small cell lung carcinoma (1); ovarian carcinoma (1); pancreatic adenocarcinoma (1); rectum adenocarcinoma (1); stomach adenocarcinoma (1); tenosynovial giant cell tumor (1); thymus cancer (1); thyroid carcinoma (1); triple-negative breast carcinoma (1); uterine carcinosarcoma (1); uterine corpus endometrial carcinoma (1).